CRP (C-reactive protein)
Diseases named in the same sentence as CRP in open-access papers (continued):
Sharing a sentence is not in itself a finding about the gene and the disease.
tumor (continued). "Laboratory tests revealed an elevated C-reactive protein and ferritin levels, while tumor markers such as AFP, CEA, CA199, CA125, CA50, and T-SPOT were negative." (PMID 39144665, 2024). "Higher levels of pks+ E. coli were associated with lower levels of the serum C-reactive protein, fewer densities of CD4+ cells and CD163+ cells in the tumor microenvironment, and a reduction in the number of organs affected by recurrent metastasis." (PMID 39272861, 2024). "In both groups of patients, biomarkers associated with improved RFS and OS were represented by higher levels of tumor mutational burden, tumor PD-L1, intratumoral CD8+ T cells and IFN-γ-associated gene signatures, and lower levels of serum C-reactive protein." (PMID 39727691, 2024). "Univariate analyses showed that fT3 or fT4, fN1 or higher, stage III or higher, R1 or more residual tumor, and higher preoperative CRP level were significantly correlated with a poor prognosis." (PMID 38999874, 2024). "Significantly higher intra-epithelial infiltration of T-bet+ cells and macrophages were seen in tumours of patients with a high CRP level compared to those with a low CRP level." (PMID 39613865, 2024). "As exogenous substances, tumor cells can induce inflammatory responses and recruit chemokines to promote the production of CRP in the liver." (PMID 39132507, 2024). "In a large number of studies focussing on various tumors, serum CRP has been identified as a factor that predicts prognosis, tumor recurrence and treatment responses." (PMID 39564003, 2024). "For instance, researchers have shown that, in the assessment of tumour prognosis, The predictive utility of the CRP/Alb ratio is comparable to that of the mGPS." (PMID 38496751, 2024). "If we summarize the data of our cohort until this point, we can statistically say that patients who had an elevated preoperative CRP level had a bigger tumor (>pT2), a higher grading (>G3), and a reduced life prognosis." (PMID 39001318, 2024). "Patients with high CRP levels (> 10 mg/l) were significantly more often diagnosed with high-grade tumours and tumours exhibiting microsatellite instability." (PMID 39613865, 2024). "Thereafter, the concentrated ROS in tumor cells induced deboronation and charge elimination of the CRP polymer." (PMID 38923275, 2024). "Results: at the time of tumor diagnosis, high inflammatory biomarkers (c-reactive protein (CRP), interleukin-6 (IL-6)) and albumin serum levels were associated with impaired OS in PDAC patients, but not in patients with oAC." (PMID 38539528, 2024). "Increased CRP levels in patients with GI cancer are positively relevant to larger tumor size, metastasis, and mortality." (PMID 39687883, 2024). "In this study, higher CRP levels were observed in patients with a right-sided or an MSI tumour, as previously reported in several papers." (PMID 39613865, 2024). "CRP also enhances tumour cell proliferation and survival by protecting them from therapy-induced apoptosis." (PMID 39498386, 2024). "CRP is a well-known marker for inflammation as well as more aggressive tumour biology and highly predictive for survival and other outcome parameters in HCC patients." (PMID 38848660, 2024). "A promising direction is the adjustment of HNSCC therapy based on dynamic changes occurring in the tumor microenvironment, including changes in the neutrophil-to-lymphocyte ratio, fluctuations in CRP values, and microsatellite instability." (PMID 39407936, 2024). "CRP and IL-6, known markers of systemic inflammation, demonstrated significant increases with disease progression, consistent with their role in the tumor microenvironment." (PMID 39816276, 2024). "Inflammation due to a tumor leads to an increase in the production of C-reactive protein (CRP) and a decrease in the synthesis of vitamin D-binding protein (important for vitamin D absorption in the intestine and transport in the vessels)." (PMID 38732007, 2024).
tumor (continued). "As for CRP/albumin, it positioned itself at a certain distance from the previous ones and at the same level as other variables, such as those dependent on the tumor." (PMID 39199720, 2024). "When combined with tumour markers, these blood values kept the same positive trends, but only CRP maintained its statistical significance (p = 0.011)." (PMID 38922374, 2024). "The results of another study showing a correlation between CRP levels and OS after stratification by disease extent contradict an increase in CRP only in the context of tumor progression." (PMID 38539528, 2024). "CRP‐treated macrophage‐conditioned medium (CRP‐MCM) enhanced tumor proliferation in both 786‐O and MAMIYA cells as compared to non‐treated MCM." (PMID 39564003, 2024). "Similar to PTX3, CRP contributes to tumor progression by modulating the tumor microenvironment, particularly through angiogenesis and inflammatory responses." (PMID 39594709, 2024). "The nomogram model based on SII, PNI, tumor size, tumor necrosis, surgical mode, pathological type, CRP, AJCC stage and Fuhrman grade has good accuracy, discrimination and clinical prediction efficiency." (PMID 39443568, 2024). "The analysis revealed the impact of clinical parameters (primary tumor site, presence of non‐bone metastases, steroid and opioid use, food intake, and BMI) and laboratory parameters (IL‐8, chloride, CRP, WBC, and lymphocytes) on overall survival." (PMID 39390750, 2024). "There previous reports support the present findings that CRP is a predictive factor for poor tumor response and shorter PFS." (PMID 38365678, 2024). "Peripheral lymphocyte and neutrophil percentages, serum C-reactive protein (CRP) expression, tumor size, and tumor pathology are the prognostic factors of OS for newly diagnosed stage III/IV NSCLC patients." (PMID 38841570, 2024). "In conclusion, preoperative SII, PNI, tumor size, tumor necrosis, surgical mode, pathological type, CRP, AJCC stage and Fuhrman grade are closely related to the postoperative prognosis of patients with RCC." (PMID 39443568, 2024). "CRP (C-reactive protein) levels were determined by immunoturbidimetry, while levels of classical tumor markers were measured using CMIA (Chemiluminescence Microparticle Immunoassay)." (PMID 37848726, 2023). "In combination, these data reinforce the correlation of IL-6 and the adenosine pathway in advanced NSCLC and the use of high CRP as a surrogate for an immunosuppressive TIME (tumor immune microenvironment)." (PMID 37852738, 2023). "This seems interesting, since parameters such as CRP and NLR have been evaluated thoroughly and their elevation has been linked to impeded survival in other tumor entities." (PMID 37977000, 2023). "The other explanation for the subsequent decrease in CRP levels was an improved immune status in the tumour microenvironment." (PMID 39516365, 2023). "A poor prognosis can be associated with elevated levels of markers including C-reactive protein (CRP) and interleukin-6 (IL-6), which indicate systemic inflammation and link it to tumor aggressiveness and decreased overall survival." (PMID 37892820, 2023). "We also showed that the acute inflammatory markers of erythrocyte sedimentation rate, C-reactive protein, and fibrinogen, and the tumor markers of CEA and CA 19.9 can be useful in diagnosis and prognosis in patients with CRC." (PMID 38137862, 2023). "Laboratory examinations revealed elevated immunoglobulin G and C-reactive protein, and normal serum levels of tumor markers and interleukin-6." (PMID 38082371, 2023). "Our successfully developed tumor dynamics-biomarker model adequately characterized the longitudinal CRP concentrations, providing a link between chemotherapy-driven TS and CRP." (PMID 38001689, 2023). "In this cohort, patients with more advanced disease and higher tumor burden had poorer performance status and concomitantly lower levels of albumin and higher levels of CRP." (PMID 37176111, 2023).
tumor (continued). "Evaluating other established prognostic markers of survival and recurrence, we found that CRP, tumour grade, tumour size, and age at diagnosis were all significant prognostic factors for both recurrent disease and overall survival." (PMID 36900335, 2023). "The main factors for the prognosis of metastasis that are currently used are TNM classification, G grade of tumor differentiation, C reactive protein, neutrophil-to-lymphocyte ratio, and several other clinical signs in different prognostic models." (PMID 37443682, 2023). "The growth of tumor cells stimulates the host to secrete interleukin-6 and other inflammatory factors, thereby increasing the synthesis of CRP in the liver." (PMID 37137949, 2023). "OS in the whole cohort was analyzed separately according to the patient's peripheral blood CRP levels (taken within +/− 4 weeks from tumor sampling used for PD‐L1 analysis) and tumor PD‐L1 TPS score." (PMID 37329173, 2023). "Multimarker models such as the Glasgow Prognostic Score (albumin and CRP) seem to have some potential at predicting tumor response to neoadjuvant CRT." (PMID 36766755, 2023). "A prognostic profile was composed based on the categorical variables CRP and tumour grade, as well as macrophage biomarkers sCD163 and sSIRPα (prognostic markers for both overall survivals)." (PMID 36900335, 2023). "Our coupled tumor dynamics-CRP model predicted TS and CRP concentrations across the whole duration of treatment." (PMID 38001689, 2023). "Risk factors that decreased the efficacy in medical management included the presence of appendicolith, neoplasm, appendiceal dilatation, peri-appendiceal fluid collection, higher mean temperature, CRP, and bilirubin." (PMID 37790034, 2023). "Further, low PNI correlated significantly with older age, lower BMI, larger tumor size, and elevated CRP levels." (PMID 37197130, 2023). "As expected, the level of inflammation assessed by LCR, CAR, and CRP increased with increasing tumor stage." (PMID 36875131, 2023). "The aim of the study was to analyze the prognostic and predictive value of CRP in addition to traditional prognostic and predictive markers and tumor PD‐L1 score." (PMID 37329173, 2023). "Several pan-biomarkers have been identified, including C-reactive protein (CRP), microRNAs, circulating tumor cells (CTCs), DNA methylation patterns, metabolites, and telomere length." (PMID 38002346, 2023). "In conclusion, we found that during PC progression, the exocrine is more vulnerable than the endocrine; FGG+CRP+ iCAFs displace the islets in the tumor stroma; the fibroblasts at the tumor edge showed immunoenhancement behaviors." (PMID 37124494, 2023). "Nevertheless, consistent with previous findings linking high CRP with poor outcomes, our data indicate a correlation between elevated CRP levels and aggressive tumor behavior, with independent prognostic relevance." (PMID 38053048, 2023). "We characterized the association between anticancer drug exposure, tumor size as a marker of tumor dynamics, and CRP as a marker of inflammation and derived different predictors." (PMID 38001689, 2023). "Currently, at the age of 3.5 years, the patient still presents with recurrent episodes of skin rash and systemic inflammation (CRP of 33 mg/L) and prednisolone dose is at 0.44 mg/kg/day." (PMID 37600812, 2023). "The tumor-promoting activity of PLCD3 was investigated by in vitro tests since it is a crucial gene in the CRP score." (PMID 37007130, 2023). "Along with the known prognostic factors tumour grade and CRP, these biomarkers comprised an excellent prognostic profile, associated with almost no relapse or death in the low-risk group and a five-year survival rate of 45 percent in the high-risk group." (PMID 36900335, 2023). "Lastly, we took a closer look at the C-reactive protein (CRP) measured before surgery and correlated it with the total cholesterol values of our tumor patients." (PMID 37024569, 2023).
tumor (continued). "A prognostic profile was made based on sCD163 and sSIRPα; it also included c-reactive protein and tumour grade." (PMID 36900335, 2023). "We also observed a significant interaction between inflammation (assessed by LCR, CAR, and CRP), tumor stage, and overall survival." (PMID 36875131, 2023). "CRP and tumor type were consistently ranked first and third in variable importance using two different variable importance measure methods (increase in mean square errors and increase in node purity), respectively." (PMID 35871390, 2023). "In the standard clot formation assay, correlations between Vmax and fibrinogen, CRP, and tumor marker Ca 19-9 levels were found, and in the standard assay, a strong correlation between ΔAbs and fibrinogen levels was found." (PMID 37627058, 2023). "The changes in CEA and CRP circulating values 1 year after surgery suggest a decrease in tumor burden after surgery." (PMID 36979873, 2023). "A multivariate logistic regression analysis for the prediction of early death was performed using the following variables: a smoking history, ECOG PS, the histological type, liver metastasis, tumor size, neutrophils, lymphocytes, sNLR, CRP, and albumin." (PMID 35871700, 2023). "CRP level is also correlated with both tumor and nodal stage and histopatological differentiation of the tumor." (PMID 38040848, 2023). "CRP has been shown to have prognostic value in predicting outcomes, as well as the ability to predict response to chemotherapy in various tumor types." (PMID 37176111, 2023). "At the univariate analysis for OS, Child-Pugh class, tumor size, previous surgery, CRP, PNI, therapeutic regimen, therapeutic effect evaluation substantially influenced the OS." (PMID 37612634, 2023). "Statistically significant associations of levels of tumor markers at the time of diagnosis and death were observed for CA125, HE4, CRP, PCT and Il-6." (PMID 37373969, 2023). "IL-6 induces the activation of STAT3 and NF-κB by CRP and specific acute phase response proteins, preventing apoptosis and thus promoting tumor cell proliferation." (PMID 37719018, 2023). "Elevated blood CRP levels have been used as an invasive index of any ongoing inflammatory response, however its increase is proposed to contribute to tumor progression through reactive oxygen species and cytokine signaling in the tumor microenvironment." (PMID 37024778, 2023). "CRP or hs-CRP is a crucial inflammatory factor, and few studies have been conducted on serum CRP or hs-CRP in tumor nutrition." (PMID 37293590, 2023). "In recent years, there have been many researches on the relationship between pre-treatment inflammatory indicators and tumor prognosis, such as CRP, neutrophils-platelet score, the CRP/Alb ratio, GPS, mGPS, HS-GPS and so on." (PMID 37735699, 2023). "This score is based on C-reactive protein (CRP) and albumin levels to predict tumor aggression and patient prognosis." (PMID 37662604, 2023). "In a cross-sectional study of women with metastatic breast cancer, circulating tumor cells positively correlated with CRP (r=0.22; P=0.02) and IL6 (r=0.25; P=0.01)." (PMID 38148846, 2023). "Taken together, we provide evidence for the existence of the monomeric form of CRP in CC being expressed exclusively within tumor tissue, primarily in systemically inflamed patients." (PMID 37006231, 2023). "CRP can predict mortality, treatment outcomes, and tumor recurrence in solid tumor renal cell carcinoma and other digestive tumors, while preoperative concentrations can predict survival after partial nephrectomy." (PMID 37873776, 2023). "Albumin synthesis decreases in response to the production of some inflammatory factors involved in tumor immunity and the acute phase response, such as tumor necrosis factor, interleukin-6, and C-reactive protein (CRP)." (PMID 37576904, 2023).
tumor (continued). "The process of bone metastasis development begins with colonisation when circulating tumour cells, along with the help of inflammatory biomarkers such as CRP and ALP, enter the bone marrow compartment and engage in specialised microenvironments or niches." (PMID 37489216, 2023). "Our multicentre, large-cohort study elucidates that elevated preoperative levels of CRP and AFP are significantly associated with the more aggressive biological tumor behavior and inferior prognosis following hepatectomy." (PMID 38053048, 2023). "Multivariable Cox regression analysis considering age, extent of resection, KPS, tumor size, and baseline CRP confirmed that an elevated CRP level (≥ 3.14 mg/dl) is an independent predictor of shortened PFS (HR: 7.20, 95% CI 1.08–48.14, p = 0.04)." (PMID 34882287, 2022). "If the tumor exhibits inflammatory features, sinusoidal dilatation, thick arteries, and pseudoportal tracts, CRP and/or SAA is first requested and will lead to the diagnosis of IHCA, if overexpressed." (PMID 35954333, 2022). "In mCRPC patients treated with [177Lu]Lu-PSMA I&T, baseline CRP, LDH, AST, and time interval until RLT initiation (thereby reflecting a possible indicator for tumor aggressiveness) are independently associated with survival." (PMID 35650263, 2022). "We examined the prognostic value of MMP-8 immunoexpression in tumour tissue and the amount of MMP-8-positive polymorphonuclear cells (PMNs) in PDAC and their association with immune responses using C-reactive protein (CRP) as a marker of systemic inflammation." (PMID 35328734, 2022). "We investigated numerous clinical features, including tumor status, demographic information, and laboratory tests (e.g., creatinine, estimated glomerular filtration rate, albumin, hemoglobin, and C-reactive protein)." (PMID 35804319, 2022). "C-reactive protein (CRP) is an inflammation-related prognostic biomarker that can predict tumor recurrence and treatment response in adult solid tumors." (PMID 34882287, 2022). "Although MMP-8 immunoexpression in the tumour seems to represent an independent prognostic factor, the combination of the CRP level and MMP-8 expression offers more precise prognostic information." (PMID 35328734, 2022). "Meanwhile, significant changes in humoral immunity characterized by a decrease in immunoglobulins (IgA, IgG, and IgM) levels and an increase in the CRP level occurred after neurosurgical tumor resection." (PMID 36169250, 2022). "CRP is an acute phase protein synthesized in the liver that can stimulate inflammatory cytokines and lead to tumor deterioration." (PMID 36194563, 2022). "Prior works also discovered that the neutrophil-to-lymphocyte ratio (NLR) and C-reactive protein (CRP) are important factors leading to muscle decomposition among tumor cases." (PMID 35215488, 2022). "Among those biomarkers, the PLR, NLR, and CRP are derived from hematological components of the systemic inflammatory response that can reflect the inflammatory state between the tumor and host." (PMID 35558519, 2022). "Neutrophil-to-lymphocyte ratio (NLR), platelet-to-lymphocyte ratio (PLR), C-reactive protein (CRP), and Glasgow prognostic score (GPS) are closely associated with postoperative outcomes in patients who undergo tumor resection." (PMID 35431888, 2022). "In the present study, serum immunoglobulins (IgA, IgG, and IgM), CRP, and complements (C3 and C4) levels were determined to evaluate the effects of neurosurgical tumor resection on humoral immunity." (PMID 36169250, 2022). "According to our findings, a high number of MMP-8-positive PMNs in a tumour together with low CRP levels indicate a better prognosis compared to the absence of PMNs and an elevated CRP level." (PMID 35328734, 2022). "Immunepotent CRP (ICRP) is a mixture of substances that were shown to have cytotoxic activity on different tumor cell lines in vitro and can modulate the immune response." (PMID 36012593, 2022).